ITGA2 (integrin subunit alpha 2)
Description:
Integrin alpha-2/beta-1 is a receptor for laminin, collagen, collagen C-propeptides, fibronectin and E-cadherin. It recognizes the proline-hydroxylated sequence G-F-P-G-E-R in collagen. It is responsible for adhesion of platelets and other cells to collagens, modulation of collagen and collagenase gene expression, force generation and organization of newly synthesized extracellular matrix. (Microbial infection) Integrin ITGA2:ITGB1 acts as a receptor for Human rotavirus A. (Microbial infection) Integrin ITGA2:ITGB1 acts as a receptor for Human echoviruses 1 and 8.
Synonyms: GPIa; CD49b; VLAA2; HPA-5; BR; FMAIT3; VLA-2
Tractability: Small molecule: a high-quality ligand is known; it belongs to a druggable protein family. Antibody: a drug acting on it is in phase 2 or 3 trials; its Gene Ontology location is reachable by antibodies, with high confidence; UniProt predicts a signal peptide or a membrane-spanning region. PROTAC: ubiquitination databases record sites on it; its protein half-life has been measured; a small molecule that binds it is known.
Target class: Adhesion
Gene: Protein-coding gene on chromosome 5 (52,989,320 to 53,094,779, forward strand). Ensembl gene ENSG00000164171.
Subcellular location: Membrane
Pathways (Reactome):
Extracellular matrix organization: ECM proteoglycans; Integrin cell surface interactions; Laminin interactions; Syndecan interactions
Developmental Biology: CHL1 interactions; Regulation of MITF-M-dependent genes involved in extracellular matrix, focal adhesion and epithelial-to-mesenchymal transition
Hemostasis: Platelet Adhesion to exposed collagen
Signal Transduction: MET activates PTK2 signaling
Gene Ontology:
Molecular function: collagen binding; collagen binding involved in cell-matrix adhesion; collagen receptor activity; protein binding; protein-containing complex binding; amyloid-beta binding; heparan sulfate proteoglycan binding; signaling receptor activity; integrin binding; laminin binding
Biological process: cell adhesion mediated by integrin; cell-matrix adhesion; cell-substrate adhesion; collagen-activated signaling pathway; integrin-mediated signaling pathway; mesodermal cell differentiation; substrate-dependent cell migration; animal organ morphogenesis; blood coagulation; cell adhesion; cell-cell adhesion; extracellular matrix organization; cellular response to estradiol stimulus; cellular response to mechanical stimulus; detection of mechanical stimulus involved in sensory perception of pain; female pregnancy; focal adhesion assembly; hepatocyte differentiation; hypotonic response; mammary gland development; positive regulation of cell adhesion; positive regulation of cell projection organization; positive regulation of collagen biosynthetic process; positive regulation of epithelial cell migration; positive regulation of leukocyte migration; and 14 more
Cellular component: cell surface; focal adhesion; integrin alpha2-beta1 complex; plasma membrane; integrin complex; axon; axon terminus; basal part of cell; external side of plasma membrane; membrane; perinuclear region of cytoplasm; presynapse
Genetic constraint (gnomAD): Loss-of-function variants: 76 observed, 116.65 expected, observed/expected ratio (o/e) 0.65, 90% interval 0.54 to 0.79. The upper end of that interval is the gene's LOEUF score, 0.79, which puts it in group 3 of 6, group 1 being the genes least tolerant of losing a copy. Missense variants: 1,109 observed, 1,286.7 expected, observed/expected ratio (o/e) 0.86, 90% interval 0.82 to 0.91. Synonymous variants: 432 observed, 455.4 expected, observed/expected ratio (o/e) 0.95, 90% interval 0.88 to 1.03.
Homologues: Orthologues: chimpanzee ITGA2 (98% identical), macaque ITGA2 (98% identical), pig ITGA2 (87% identical), dog ITGA2 (87% identical), rabbit ITGA2 (87% identical), mouse Itga2 (82% identical), guinea pig ITGA2 (82% identical), rat Itga2 (82% identical), tropical clawed frog itga2 (60% identical), zebrafish itga2.2 (50% identical), Drosophila melanogaster if (19% identical), Drosophila melanogaster scb (19% identical), and 5 more. Paralogues in human: ITGA1 (40% identical), ITGA11 (34% identical), ITGA10 (33% identical), ITGAX (26% identical), ITGAM (26% identical), ITGAD (25% identical), ITGAL (25% identical), ITGAE (23% identical), ITGA8 (21% identical), ITGA7 (20% identical), ITGA9 (20% identical), ITGA4 (20% identical), and 5 more.
Diseases named in the same sentence as ITGA2 in open-access papers:
ITGA2 is named in the same sentence as 188 diseases in open-access papers, as found by Europe PMC text mining. Sharing a sentence is not in itself a finding about the gene and the disease. The quoted sentences say what the papers report.
breast carcinoma (48 papers, 1998 to 2025). "In support, studies have shown that the T188I mutation in ITGB1 contributed to neoplasia by over-activating ERK/MAPK signaling, and mutations in ITGA2 were associated with an increased risk of prostate, oral, and breast cancers." (PMID 39436262, 2024). "In the breast cancer subtype, the high expression of ITGA2 was variable and was associated with metastases and poor survival." (PMID 35936750, 2022). "In breast cancer, ITGA2 has been linked to tumor aggressiveness, cancer progression (via EMT—epithelial–mesenchymal transition), and metastatic ability." (PMID 35936750, 2022). "The gene encoding integrin α2 chain (ITGA2) is described in the occurrence and progression of multiple cancers, including colorectal cancer, lung cancer, and breast cancer." (PMID 35936750, 2022). "Recent studies showed that the ITGA2 gene over-expression is associated with increased risks of prostate cancer, breast cancer and gastric cancer." (PMID 29743821, 2018). "Previous studies have shown that the ITGA2 gene is associated with various types of cancer, including colorectal cancer, prostate cancer, hepatocellular carcinoma, pancreatic cancer, breast cancer, melanoma and ovarian carcinoma." (PMID 28947976, 2017). "ITGA2 protein level was inversely associated with miR-373 level in breast cancers (r = -0.663, P<0.001)." (PMID 26258411, 2015). "The loss of ITGA2 is involved in metastasis in colon cancer and breast cancer cells." (PMID 38028209, 2023). "Additionally, the ITGA2 BglII polymorphism has been associated with increased risk for higher disease stages of breast cancer, positive history for oral cancer, and prevalence of diabetic retinopathy, myocardial infarction, and stroke." (PMID 35936750, 2022). "ITGA2 protein level was inversely associated with miR-373 level in breast carcinomas." (PMID 26258411, 2015). "ITGA2 protein level was inversely associated with miR-373 level in breast cancers." (PMID 26258411, 2015). "Altogether, these observations show that ITGA2 level was negatively associated with miR-373 level, miR-373-regulated ITGA2 translation inhibition is relevant to metastasis in breast cancer, and miR-373high/ITGA2low may be as a prognosis biomarker for breast cancer patients." (PMID 26258411, 2015). "In this study, we found that PSAT1 is significantly highly expressed in ER-negative breast cancer and was able to promote breast cancer cell metastasis by regulating the ITGA2 protein." (PMID 39199378, 2024). "Accordingly, the role of ITGA2/ITGB6-PI3K/Akt in HER2+ breast cancer cells and its modulation by PGB-0-ol warrant further investigation." (PMID 38028209, 2023). "Tumor ITGA2 expressions have been correlated with hypermethylation in prostate cancer and hypomethylation in breast cancer." (PMID 35936750, 2022). "ITGA2 reportedly is involved in the occurrence and progress of multiple cancers, including colorectal cancer, hepatocellular carcinoma, and breast cancer." (PMID 34778054, 2021). "More recently, concomitant upregulation of ITGA2 and increased levels of sialylated bi- and tri- antennary N-glycans was correlated with metastatic potential in breast cancer cell lines using glycomics." (PMID 34646995, 2021). "Comprehensive RNA sequencing data collected as a part of the MET500 cohort was analyzed for gene expression of Gli2, PTHLH, ITGB1, and ITGA2 in metastatic breast cancer samples." (PMID 34199096, 2021). "One study indicates that a higher ITGA2 protein level was detected in breast cancers and that an increased expression of ITGA2 was positively bound up with increased metastatic ability in breast cancer." (PMID 34778054, 2021). "A parallel study of integrin expression in the PMC42-ET breast cancer cell line induced to undergo EMT with EGF indicated that ITGA2 and ITGB1, and their downstream regulator ILK, appeared to be upregulated." (PMID 33276802, 2020).
breast carcinoma (continued). "ITGA2 is overexpressed in several types of tumors, such as pancreatic cancer, gastric cancer, liver cancer, prostate cancer, and breast cancer." (PMID 31818309, 2019). "Consistent with this fact, our results revealed that ITGA2 was abnormally over-expressed in many malignant tumors, including pancreatic cancer, gastric cancer, liver cancer, and breast cancer." (PMID 31818309, 2019). "Alpha-V integrin (ITGAV) has been associated with brain metastasis, but the relationship between ITGA2/3 and breast cancer brain metastasis has not well known yet." (PMID 31758065, 2019). "Loss of ITGA2 expression is frequently observed in solid tumors, and the silencing of ITGA2 resulted in enhanced breast cancer migration." (PMID 28068967, 2017). "11/15 (73.33%) of breast cancer patients with high miR-373 and low ITGA2 expression exhibited the LN-positive metastases." (PMID 26258411, 2015). "We also found that the mRNA level of ITGA2 was slightly reduced in breast cancers versus normal breast tissues (P = 0.038)." (PMID 26258411, 2015). "Most of breast cancer patients with high miR-373 and low ITGA2 expression exhibited the lymph node-positive metastases." (PMID 26258411, 2015). "73.33% of breast cancer patients with high miR-373 and low ITGA2 expression exhibited the lymph node-positive metastases." (PMID 26258411, 2015). "In this study, we found that the reduction degree of ITGA2 protein was far more than that at the mRNA level in breast cancers." (PMID 26258411, 2015). "We here found that ITGA2 protein level was significantly reduced in breast cancers compared the adjacent normal breast tissues, and ITGA2 silencing induced cancer migration, suggesting that the reduction of ITGA2 in primary cancer aided cancer metastasis." (PMID 26258411, 2015). "MDA-MB-231 breast cancer cell lines express high levels of ITGA2 / ITGB1, ITGA3 / ITGB1, ITGA5 / ITGB1, ITGAV / ITGB3 integrins, compared to MCF-7, T47D, and ZR75-1 breast cancer cells." (PMID 25593998, 2014). "ITGA2 also plays a role in breast cancer by promoting metastasis." (PMID 40940954, 2025). "PSAT1 could increase distant breast cancer metastasis through upregulation of the p-AKT/SP1/ITGA2 axis." (PMID 39199378, 2024). "Mechanistically, PSAT1 facilitated breast cancer metastasis via the p-AKT/SP1/ITGA2 axis." (PMID 39199378, 2024). "Therefore, we suggest that PSAT1 affects breast cancer metastasis by regulating the expression of ITGA2." (PMID 39199378, 2024). "ITGA2 silencing has previously been shown to stimulate breast cancer migration." (PMID 37280313, 2023). "In addition, the expression of ITGA2 in tissues collected from breast cancer patients was lower in lymph node-positive compared to lymph node-negative metastases." (PMID 32824235, 2020). "Furthermore, using the GEPIA web tool, we found that the mRNA expression levels of ITGA2 correlated positively with PD-L1 levels in several malignant tumors, including pancreatic, liver, gastric, and breast cancers." (PMID 31818309, 2019). "Correlations of ITGA2 expression with clinicopathological status in 53 patients with breast cancer." (PMID 26258411, 2015). "We found that ITGA2 knockdown could rescue the inhibitory effects of the inhibition of miR-373 on breast cancer cell migration." (PMID 26258411, 2015). "Together, our results show that epigenetic silencing of ITGA2 by miR-373 stimulates breast cancer migration, and miR-373high/ITGA2low may be as a prognosis biomarker for breast cancer patients." (PMID 26258411, 2015). "Taken together, our observations revealed that ITGA2 protein level is significantly reduced in breast cancers, especially in breast cancers with the LN-positive metastases, and its reduction might play an important role in cancer invasion and metastasis." (PMID 26258411, 2015). "Breast cancer patients with high miR-373 and low ITGA2 exhibited the LN-positive metastases." (PMID 26258411, 2015).
breast carcinoma (continued). "The absence of ITGA2 not only results in loss of the quiescence phenotype, but also activates cellular programs associated with cell migration in animal models of prostate, gastric, colorectal, and breast cancer." (PMID 37206200, 2023). "In the present study, we identified differentially expressed genes, including ITGA2, by transcriptome sequencing of PSAT1-overexpressing breast cancer cell lines." (PMID 39199378, 2024). "Worthy, the signature demonstrated to predict poor outcomes in breast cancer patients exhibiting high transcriptional levels of ITGA11, THBS1, FN1, EMP1, ITGA2, FYN, SPP1, and EMP2." (PMID 38937754, 2024). "The reduced migration in siRNA-ITGA2 PANC-1R cells overexpressing ITGA2 is in line with previous studies, which reported a decreased migration in PDAC, gastric and breast cancer cell lines upon silencing of this gene." (PMID 36765586, 2023). "The low expression of HSD17B11 and ITGA2 and the high expression of VIM and ABHD17C have all been validated by recent sequencing studies on breast cancer, reflecting the accuracy of these two rules." (PMID 31456818, 2019). "Several top up-regulated genes were associated with motility, adhesion, invasiveness, and metastasis in breast cancer or other cancers, such as GBP1, ITGB6, ITGA2, and matrix metalloproteases MMP10 and MMP1." (PMID 27351228, 2016). "Additionally, analysis of whole exome sequencing of tumor biopsies from the Metastatic Breast Cancer Project showed a decrease in copy number of ITGB1 and variable expression of ITGA2 between primary tumors, soft tissue metastases, and bone metastases." (PMID 34199096, 2021). "Whole exome sequencing of tumor biopsies from patients collected under the Metastatic Breast Cancer Project revealed that metastatic primary tumors have higher ITGA2 and ITGB1 copy number compared to non-metastatic primary tumors." (PMID 34199096, 2021). "Additionally, the activation of integrin signaling via binding of THBS4 to ITGA2 may contribute to activation of Wnt/β-catenin pathway as ITGA2 has been shown to be instrumental for platelet-induced activation of Wnt/β-catenin signaling in MCF7 breast carcinoma cells." (PMID 34631719, 2021). "Although the EMT-associated ITGB1, ITGA2 and ILK are not essential for EGF-induced EMT in PMC42-ET cells, they are necessary for breast cancer cell adhesion to ECM-substrates and cellular movement." (PMID 33276802, 2020). "The up-regulation of ITGA2 and ITGA3 observed in this study in brain seeking breast cancer cell line 231BR may provide a potential indicator for breast cancer metastasis, and better understand the role integrin plays in this critical bioprocess." (PMID 31758065, 2019). "Thus, ITGA2 and ITGB5 can be considered as therapeutic biomarkers for the prognosis of breast cancer." (PMID 28587194, 2017). "A negative correlation was observed between miR-373 and ITGA2 in breast cancers (r = -0.663, P<0.001), and no patients showed higher ITGA2 level in breast cancer patients with higher miR-373." (PMID 26258411, 2015). "In this study, we found that a lower ITGA2 protein level was observed in breast cancers compared to adjacent non-cancerous breast tissues." (PMID 26258411, 2015). "A lower protein level of ITGA2 was detected in primary breast cancers relative to adjacent non-cancerous breast tissues (P<0.001); however, ITGA2 was recovered in lymph node metastases compared to the primary cancers (P<0.001)." (PMID 26258411, 2015). "CTGF plays a vital role in chondrocyte proliferation, combined with the previous study on the role of TTBK2 in regulating the cell proliferation, together with ITGA2 and CTGF, TTBK2 may coordinate the adhesion and proliferation of the migrated breast cancer cells in the bone subsequent lesion." (PMID 35685372, 2022).
breast carcinoma (continued). "Recently, it has been reported that C-reactive protein (CRP) induced upregulation of ITGA2 and matrix metalloproteinase-9 (MMP-9) expressions by activating focal adhesion kinase, pilin, and ERK signal pathway, thus promoting the invasion of breast cancer cells." (PMID 32904605, 2020). "We found that TGFβ stimulation increased the binding of ΔNp63 to LAMB3, ITGA2 and SERPINE1 loci in MCF10A MII cells and in HCC1954 breast cancer cells without affecting ΔNp63 mRNA expression." (PMID 39180088, 2024). "Assessment of ITGA2/B1 and ILK expression in a published Luminal breast cancer dataset was not consistent with the pro-aggressive implications of our association with EMT in the EDW-01 PDX, since ILK predicted improved regression-free survival post treatment." (PMID 33276802, 2020). "Spearman correlation analysis of gene signatures in metastatic biopsies of breast cancer reveal a significant (p < 0.001) negative correlation between PTHLH and ITGA2 (p < 0.001), PTHLH and ITGB1 (p < 0.01), Gli2 and ITGA2 (p < 0.001), and Gli2 and ITGB1 (p < 0.0001)." (PMID 34199096, 2021).